PARP14 (poly(ADP-ribose) polymerase family member 14)
Diseases named in the same sentence as PARP14 in open-access papers (continued):
Sharing a sentence is not in itself a finding about the gene and the disease.
melanoma (5 papers, 2020 to 2025). A malignant, usually aggressive tumor composed of atypical, neoplastic melanocytes. "Melanoma patients with high expressions of Wdfy4, Parp14, Cybb, Itgb2, and Itgam were found to be associated with the longer OS time in melanoma." (PMID 33679872, 2020). "PARP14 upregulation has been observed in melanoma cell cultures derived from patient tumors resistant to immunotherapy with elevated IFNγ signaling." (PMID 40195501, 2025). "Colocalization of p62, PARP14, and ADPr was also observed in the melanoma cell line A375 following IFNγ treatment (Fig. EV3H), suggesting that this phenomenon is not restricted to lung cells." (PMID 40195501, 2025). "RNA-seq analysis revealed upregulation of PARP14 expression in multiple human and mouse tumour cell lines chronically exposed to IFNγ as well as in IFNGhigh melanoma tumours, suggesting that PARP14 is an IFNγ target gene." (PMID 37752135, 2023). "Using immunoprecipitation, we detected an interaction between STAT1 and PARP14 in three melanoma cell lines—MV3, LOX-IMVI, and YUMM2.1." (PMID 37752135, 2023). "In addition, the mRNA abundance of PARP14 in both melanoma cells and patient samples (TCGA SKCM) positively correlated with that of STAT1, IFNG, and CD274." (PMID 37752135, 2023). "The PPI network analysis revealed that 6 hub genes, comprising Itgb2, Wdfy4, Itgam, Cybb, Mmp2, and Parp14, might be key candidate genes related to the pathogenesis of melanoma." (PMID 33679872, 2020). "As ADPr-containing p62 bodies are also observed in melanoma cells following IFNγ treatment—and that such ADPr/PARP14 condensation is lost upon RBN treatment—understanding how PARP14-mediated ADP-ribosylation in p62 bodies functions could open new avenues for overcoming immunotherapy resistance." (PMID 40195501, 2025). "The DFS time analysis revealed that there was a similar trend that high expressions of Wdfy4, Parp14, Cybb, Itgb2, and Itgam were correlated to longer DFS time in melanoma." (PMID 33679872, 2020). "Consequently, induction of PARP14 mRNA mirrored IFNG and STAT1 mRNA in on-treatment melanoma biopsies." (PMID 37752135, 2023). "We observe upregulation of poly-ADP ribosyl polymerase 14 (PARP14) in chronic IFNγ-treated cancer cell models, in patient melanoma with elevated IFNG expression, and in melanoma cell cultures from ICBT-progressing lesions characterised by elevated IFNγ signalling." (PMID 37752135, 2023).
atherosclerosis (4 papers, 2016 to 2024). A disease characterized by the build-up of fatty material and calcium deposition in the arterial wall resulting in partial or complete occlusion of the arterial lumen. "Moreover, significant acceleration of acute arterial lesion formation and chronic atherosclerosis was observed in the mice reconstituted with PARP14−/− bone marrow." (PMID 27796300, 2016).
atopic dermatitis (4 papers, 2023 to 2025). "PARP14 inhibitors (such as RBN-3143) have shown therapeutic potential for atopic dermatitis (AD) in preclinical studies and can reduce the level of inflammatory factors, including Th17 cytokines." (PMID 41460301, 2025). "There has been growing interest in PARP14 as a potential target in allergic inflammation and tumors.PARP14’s role in inflammatory diseases including atopic dermatitis (AD), emphysema and asthma.PARP14 also plays an important role in tumors." (PMID 37650946, 2023). "In addition, RBN-3143, as a PARP14 inhibitor, is being used in clinical trials to treat atopic dermatitis, which primarily relieves symptoms in patients with atopic dermatitis by controlling inflammation." (PMID 41460301, 2025). "Nevertheless, a phase-I trial has been initiated to test the PARP14/ARTD8 inhibitor, RBN-3143, as a potential therapy for atopic dermatitis (Clinical Trial No.: NCT05215808), focusing on inflammation control." (PMID 37513811, 2023).
breast carcinoma (4 papers, 2022 to 2024). "In cluster 1, breast cancer cell markers, including Nob1, Vmp1, Crk, Ckap2, Parp14 and Mfn1, were detected among the top cluster markers." (PMID 39054536, 2024). "Here, we set out to investigate how the inhibition of ADP-ribosylation affects the TAM phenotype and show that PARP14 plays a key role in breast cancer-induced MΦ polarization." (PMID 38612413, 2024). "An interesting corollary to our findings is that preventing the development of the TAM phenotype (e.g., by PARP14 inhibition) may also increase the efficacy of the PARPi treatment of BRCA mutant breast cancer." (PMID 38612413, 2024). "This may imply that PARPis targeting both DNA-damage-responsive PARPs (PARP1 and 2) and PARP14 may possess increased antitumor potential in breast cancer." (PMID 38612413, 2024). "Our findings suggest that targeting PARP14 may have a therapeutic potential in breast cancer by reprogramming tumor-growth-promoting macrophages towards an anti-cancer phenotype." (PMID 38612413, 2024). "In a murine model of TAM polarization (4T1 breast carcinoma cell supernatant transfer to primary MΦs) and in a human TAM model (spheroids formed from JIMT-1 breast carcinoma cells and THP-1-MΦs), both PARPis and the PARP14 KO phenotype caused weaker TAM polarization." (PMID 38612413, 2024). "In addition, PARP14 depletion suppressed olaparib and cisplatin-induced apoptosis in RPE1-BRCA1KO cells, as well as the cisplatin sensitivity of MDA-MB-436 patient-derived BRCA1-mutant breast cancer cells." (PMID 36030235, 2022).
COVID-19 (4 papers, 2021 to 2023). A disease caused by infection with severe acute respiratory syndrome coronavirus 2. "As PARP14 has a well-established role in immune regulation, including its dysregulation of the Th2 immune response during allergic airway diseases, this route presented itself as a potential means of PARP14 involvement in COVID-19 pathogenesis." (PMID 33467912, 2021). "If it does have a role, would PARP14 inhibition aid in the treatment of COVID-19, or would it promote viral progression?" (PMID 33467912, 2021). "In goblet cells, STAT2 and KLF5 were highly activated and upregulated in many genes with mild/moderate COVID-19, such as ISGs (PARP14 and IFI44L), whereas ELF3, SBP1, NR2F6, and SPDEF were preferentially activated in severe COVID-19 to regulate the expression of their targets." (PMID 37936693, 2023). "Patients with severe COVID-19 often display a unique pattern of immune dysregulation, causing us to consider the potential involvement of the poly (ADP-ribose) polymerase member 14 (PARP14, also known as ARTD8, BAL2 or CoaSt6)." (PMID 33467912, 2021). "Our transcriptomics and qPCR results indicated that a set of PARP family members, including Parp9, Parp10, Parp12, and Parp14, were significantly induced by SARS-CoV-2 infection in mice, similar to those in COVID-19 patients." (PMID 35487885, 2022). "Further, they observed that key driver genes, which were upregulated with COVID-19 and IBD inflammation (e.g., CXCL1, GBP4, SOCS3, PARP14, and PARP9), were downregulated following the use of infliximab." (PMID 36060521, 2022).
diffuse large B-cell lymphoma (4 papers, 2019 to 2023). "In diffuse large B-cell lymphoma (DLBCL), PARP14 regulated the IL-4-STAT6 signaling pathway, enhanced the expression of several downstream genes, and enabled DLBCL tumor cell survival." (PMID 37650946, 2023).
glioblastoma (4 papers, 2015 to 2025). The most malignant astrocytic tumor (WHO grade IV). "We compared protein expression of PARP14 and its binding partner, DTX3L, proteins in a panel of different cell lines, (HNSCC; Glioblastoma GBM; Prostate Adenocarcinoma PRAD; and Pancreatic Adenocarcinoma PAAC)." (PMID 38182103, 2024).
asthma (3 papers, 2017 to 2023). "Furthermore, PARP-14 seems to play a crucial role in asthma." (PMID 28974953, 2017).
colorectal cancer (3 papers, 2023 to 2025). A primary or metastatic malignant neoplasm that affects the colon or rectum. "The expression of PARP9, PARP12, PARP13 and PARP14 was particularly elevated in irradiated colorectal cancer HT29 cells in a microenvironment-dependent manner." (PMID 40646573, 2025). "We previously discovered that the multifractionated dose IR upregulated the expression of unconventional PARP family members including PARP9, PARP12, PARP13 and PARP14 in colorectal cancer cells grown in laminin-rich ECM 3D cell culture." (PMID 40646573, 2025). "This indicates that PARP13 may indirectly modulate treatment response by regulating PARP9 and PARP14 related pathways, emphasizing the necessity for further investigation of PARPs in colorectal cancer." (PMID 40646573, 2025). "To investigate the role of PARP genes in colorectal cancer cell response to ionizing irradiation, we generated PARP12, PARP13, and PARP14 knockout (KO) sublines of DLD1 and HT29 cells using CRISPR/Cas9 gene editing." (PMID 40646573, 2025).
glioma (3 papers, 2022 to 2024). A benign or malignant brain and spinal cord tumor that arises from glial cells (astrocytes, oligodendrocytes, ependymal cells). "The results revealed a positive correlation between the expression of genes such as ZC3HAV1, TIPARP, PARP4, PARP14, and PARP15 and the abundance of various immune cell types in gliomas." (PMID 39724285, 2024).
ovarian carcinoma (3 papers, 2022 to 2025). A malignant neoplasm originating from the surface ovarian epithelium. "Herein, we demonstrate that RACK1, an integral component of the ribosome, is MARylated by the mono(ADP-ribosyl) transferase (MART) PARP14 in ovarian cancer cells." (PMID 39760726, 2025). "Herein, we demonstrate that PARP14 is a MART that MARylates RACK1 in ovarian cancer cells to control stress granule formation and the regulation of translation under cellular stress conditions." (PMID 39760726, 2025). "Treatment with a PARP14 inhibitor or mutation of the sites of MARylation on RACK1 blocks these outcomes, as well as the growth of ovarian cancer cells in culture and in vivo." (PMID 39760726, 2025). "We also demonstrated that pharmacological inhibition of PARP14 sensitizes ovarian cancer cells to stress by inhibiting stress granule assembly." (PMID 39760726, 2025). "Our studies thus far have demonstrated that site-specific MARylation of RACK1 mediated by PARP14 is required for stress granule assembly and stress responses in ovarian cancer cells." (PMID 39760726, 2025). "Consistently, a recent report showed that PARP14 regulates SG assembly in ovarian cancer cells." (PMID 41067892, 2025). "We observed that RACK1 is MARylated by PARP14 in ovarian cancer cells." (PMID 39760726, 2025). "Together, these data show that PARP14-mediated, site-specific MARylation of RACK1 drives stress granule assembly in ovarian cancer cells." (PMID 39760726, 2025). "We observed similar regulation of PARP14-mediated RACK1 MARylation and stress granule assembly in additional ovarian cancer cell lines, SKOV3 and HCC5044 (note the reduced number of discrete G3BP1 puncta upon PARP14i treatment)." (PMID 39760726, 2025). "Collectively, our results support a PARP14/TARG1-regulated RACK1 MARylation cycle that controls stress granule assembly and disassembly in ovarian cancer cells." (PMID 39760726, 2025).
arterial diseases (2 papers, 2016 to 2020). "According to the network analysis that linked PARP9 and PARP14 with arterial disease, we performed immunohistochemistry in arterial lesions." (PMID 27796300, 2016). "As predicted, in vivo studies in Parp14−/− mice demonstrated that PARP14 participates in the pathogenesis of arterial diseases." (PMID 32029454, 2020). "Seeking additional in vivo evidence for the potential role of PARP9 and PARP14 in arterial disease involved immunohistochemical analysis of human carotid atherosclerotic plaques surgically removed by endarterectomy." (PMID 27796300, 2016). "Taken together, these findings indicate that PARP14 derived from the haematopoietic lineage, the majority of which are macrophages in arterial lesions, plays a protective role against the development of arterial diseases, which verifies our prediction by network analysis." (PMID 27796300, 2016).
brain tumor (2 papers, 2019 to 2023). "However, in another model (unstimulated delayed brain tumor cells), PARP14 overexpression led to an increase in IFNβ expression, suggesting that the effect of PARP14 can vary between different cell models and types of stimulation." (PMID 37703374, 2023). "Notably, overexpression of PARP14, but not of GFP, was also sufficient for IFN induction in delayed brain tumor (DBT) cells, which normally express very low, if any, IFN." (PMID 31095648, 2019).
colon cancer (2 papers, 2023 to 2024). "Mutations in KIAA1217, POLD1, PIEZO1, NBEAL2, DDX17, and PARP14 were significantly more prevalent in patients with colon cancer and PRShigh than in those with PRSlow." (PMID 38577604, 2024). "This study showed that MARylation of HDAC1 and HDAC2 by PARP14 is required to induce expression of EP4 receptors in human colon cancer cells." (PMID 36814782, 2023). "Inhibition of PARP14 abrogates activation of the EP4 receptor and reduces proliferation of colon cancer cells, making PARP14 a good target for colon cancer therapy." (PMID 36814782, 2023).
follicular lymphoma (2 papers, 2022 to 2023). Follicular lymphoma is a form of non-Hodgkin lymphoma characterized by a proliferation of B cells whose nodular structure of follicular architecture is preserved. "For instance, a recent study suggested PARP14 inhibition as a promising approach in the treatment of follicular lymphomas with STAT6 mutations that lead to increased PARP14 expression." (PMID 37832523, 2023).
head and neck squamous cell carcinoma (2 papers, 2024 to 2025). A squamous cell carcinoma that arises from any of the following anatomic sites: lip and oral cavity, nasal cavity, paranasal sinuses, pharynx, larynx, and salivary glands. "We have explored further the molecular requirements of PARP9/DTX3L and PARP14 mediated survival using head and neck squamous cell carcinoma (HNSCC) and HeLa cell lines, which have increased PARP9/DTX3L and PARP14 expression." (PMID 38182103, 2024). "PARP9, its binding partner DTX3L and PARP14 protein levels are significantly correlated in head and neck squamous cell carcinoma (HNSCC) and other tumour types though a mechanism where PARP9/DTX3L regulates PARP14 post-transcriptionally." (PMID 38182103, 2024).
lung carcinoma (2 papers, 2015 to 2023). "For instance, the expression level of PARP14 positively correlated with PD-L1 in lung cancer cell lines (r = 0.491, p-value = 5.62 × 10−14)." (PMID 37628671, 2023). "In addition, we found a positive correlation between PARP14 expression level and PD-L1 in lung cancer (LUAD + LUSC) (R = 0.391 p-value < 2.2 × 10−16)." (PMID 37628671, 2023).
metastatic prostate carcinoma (2 papers, 2014 to 2024). A carcinoma that arises from the prostate gland and has spread to other anatomic sites. "It had been suggested using the PARP inhibitors DPQ or TIQ-A, that PARP14 activity is required for metastatic prostate cancer cell line survival, but these are not particularly selective and could be inhibiting other PARP family members." (PMID 38182103, 2024).
Sepsis (2 papers, 2023 to 2025). Sepsis is defined as life-threatening organ dysfunction caused by a dysregulated host response to infection. "Additionally, ZBP1, XAF1, IFI44L, SOCS1, and PARP14 were notably high in HighPANscore cells, aligning with our observations of upregulated expression of IFI44, IFIH1, IFIT1, IFIT2, and RSAD2 in lung tissues from sepsis-induced animal models." (PMID 38239341, 2023).
allergic disease (1 paper, 2023). An immune response that occurs following re-exposure to an innocuous antigen, and that requires the presence of existing antibodies against that antigen. "Among many allergic diseases, PARP14 interacted with STAT6 to enhance IL-4-induced gene expression in T cells, thereby promoting Th2 differentiation." (PMID 37650946, 2023).
Alzheimer disease (1 paper, 2025). A progressive, neurodegenerative disease characterized by loss of function and death of nerve cells in several areas of the brain leading to loss of cognitive function such as memory and language. "PARP14 inhibitors can promote the polarization of microglia to the anti-inflammatory M2 type, thereby reducing inflammation and improving cognitive function in Alzheimer's disease." (PMID 41460301, 2025).
cervical cancer (1 paper, 2023). A primary or metastatic malignant neoplasm involving the cervix. "Regrettably, our study has not yet established a correlation between mutation and expression of PARP14 in cervical cancer." (PMID 37650946, 2023). "We listed the 25 GT genes in which mutations had the greatest protective or hazardous effect on the prognosis of cervical cancer, with mutations in the PARP14 gene exhibiting a protective effect against cervical cancer." (PMID 37650946, 2023). "We found that PARP14 was significantly overexpressed at both the molecular and protein levels in cervical cancer tissues, and that higher expression of PARP14 caused better prognosis." (PMID 37650946, 2023). "The study identified PARP14 as a frequently mutated gene in cervical cancer and proposed its potential role in diagnosis and treatment." (PMID 37650946, 2023). "At the same time, we performed immunohistochemical staining of cancer tissues from a clinical cohort of 35 cervical cancer patients to analyze the qualitative and quantitative expression levels of PARP14." (PMID 37650946, 2023). "Specifically, the study focuses on PARP14, a member of GTs, and its potential as a target for tumors in the diagnosis and treatment of cervical cancer." (PMID 37650946, 2023). "Further verification was conducted through RT-qPCR and immunohistochemistry staining on cervical cancer tissues to confirm the expression of PARP14." (PMID 37650946, 2023). "Although our case sample was limited and our study was restricted to a descriptive study, the result still led us to focus on the role of PARP14 in cervical cancer." (PMID 37650946, 2023). "Our findings suggested a potential role of PARP14 in the diagnosis and treatment of cervical cancer." (PMID 37650946, 2023). "According to TCGA datasets, there was an up-regulation of PARP14 in cervical cancer when compared to normal tissues." (PMID 37650946, 2023). "This arouse our interest in investigating the role of PARP14 in cervical cancer, leading to the following related studies." (PMID 37650946, 2023). "The potential mechanism of PARP14 in cervical cancer will be explored in our further studies." (PMID 37650946, 2023).
Cirrhosis (1 paper, 2015). A chronic disorder of the liver in which liver tissue becomes scarred and is partially replaced by regenerative nodules and fibrotic tissue resulting in loss of liver function. "PARP14 levels also appear to have important clinical implications for patients with HCC, as PARP14 expression increases with disease progression from normal livers to cirrhosis and then to active stages of HCC." (PMID 26258887, 2015). "Given the positive correlation between PARP14 expression and progression of cirrhosis to HCC we speculate that during hepatocarcinogenesis, malignant hepatocytes express PARP14 to rewire their metabolism." (PMID 26258887, 2015).
colorectal adenocarcinoma (1 paper, 2021). The most common type of colorectal carcinoma. "The differential expression analysis of 5561 proteins in 95 colorectal adenocarcinoma (COAD) samples indicated high levels of TAP2 (log Fold Change [FC] = -1.33), PARP14 (logFC = -1.25), and GBP4 (logFC = -1.09) in the RSI-Low tumours." (PMID 34078917, 2021).